CGAS (cyclic GMP-AMP synthase)
Diseases named in the same sentence as CGAS in open-access papers (continued):
Sharing a sentence is not in itself a finding about the gene and the disease.
autoimmune disease (continued). "While the sensing of viral DNA by cGAS promotes beneficial antiviral responses, the detection of self-DNA and overactivation of the cGAS-STING signaling cascade are associated with autoimmune diseases." (PMID 33273464, 2020). "The DNA-dependent protein kinase (DNA-PK) catalytic subunit (DNA-PKcs) encoded by the missense mutations of protein Kinase, DNA-activated, catalytic Subunit (PRKDC) are associated with autoimmune diseases due the overactivated enzymatic activity of the cGAS." (PMID 33643304, 2020). "Our study reveals that DNA-PKcs deficiency or missense mutations result in aberrant cGAS activation that leads to overactivation of innate immunity, making cGAS a promising target to treat autoimmune diseases caused by DNA-PKcs deficiency." (PMID 33273464, 2020). "Since aberrant activation of cGAS is implicated in several autoimmune diseases, senescence and tumorigenesis, it will be important to develop means to modulate cGAS activation based on the regulatory mechanisms." (PMID 29760876, 2018). "Mouse studies that recapitulate causative mutations in the autoimmune disease Aicardi-Goutières syndrome demonstrate that ablating the cyclic GMP-AMP synthase gene abolishes the deleterious phenotype." (PMID 28963528, 2017). "Recent studies have implicated the key role of cGAS in autoimmune disease in the mouse model of Aicardi-Goutières syndrome and in the innate and adaptive immune responses in features of human lupus." (PMID 26819496, 2015). "Given the pathogenic role of dysregulated cGAS-STING signaling in autoimmune disorders, targeting TRIM21’s E3 ubiquitin ligase activity could open new avenues for developing precision therapeutics to modulate this pathway in SLE and related conditions." (PMID 40165656, 2025). "Therefore, it is vital to confirm the localization of cGAS under physiological and pathological conditions, which helps the prevention and treatment of pathogenic microbial infection, autoimmune diseases, tumors and other diseases." (PMID 38515746, 2024). "Therefore, EGCG-mediated inhibition of G3BP1 offers a potential treatment for cGAS-associated autoimmune diseases." (PMID 37354378, 2023). "Additionally, C-176 can improve inflammation and autoimmune diseases caused by abnormal activation of the cGAS-STING signaling pathway." (PMID 37081966, 2023). "cGAS is required for lethal autoimmune disease in the Trex1-deficient mouse model of AGS." (PMID 37834184, 2023). "Increasing evidence suggests that the cGAS-STING signaling pathway plays a key pathogenic role in autoimmune diseases such as systemic lupus erythematosus (SLE), rheumatoid arthritis (RA), Aicardi-Goutières syndrome (AGS), and STING-associated vasculopathy with onset in infancy (SAVI)." (PMID 37600809, 2023). "However, the recognition of self-DNA by cGAS can cause various diseases, including inflammatory and autoimmune diseases, largely due to the overexpression of IFN." (PMID 35185917, 2022). "Indeed, the DNA sensor cGAS has been reported as a key driver of lethal autoimmune disease in the Trex1-deficient mouse model of Aicardi-Goutieres syndrome (AGS)." (PMID 34125604, 2021). "Among them, the inhibitory activity of ODN A151 depends on the telomere sequence and phosphorothioate backbone to prevent cGAS activation by competing with DNA, laying the foundation for developing new immunosuppressive agents to treat autoimmune diseases caused by cGAS abnormal activation." (PMID 34867409, 2021). "However, excessive activation of the cGAS-STING signaling pathway results in autoimmune diseases, such as STING-associated vasculopathy with onset in infancy (SAVI), lupus-like disease, and Ataxia-telangiectasia (AT)." (PMID 34868032, 2021). "The loss of this negative regulation of cGAS may predispose the host to autoinflammatory or autoimmune diseases." (PMID 33643304, 2020).
autoimmune disease (continued). "Depletion of STING, IRF3, cGAS, or IFN-I receptor in TREX1-deficient mice protects against autoimmune disorders and death, indicating that cGAS–STING–IRF3 axis-regulated IFN-I production is responsible for autoimmune disorder development in TREX1-deficient mice." (PMID 31440232, 2019). "The dysregulation of cGAS activation has been implicated in several autoimmune diseases." (PMID 29760876, 2018). "cGAS is an important control point in the innate immune response; dysregulation of the cGAS pathway is linked to autoimmune diseases while targeted stimulation may be of benefit in immunoncology." (PMID 28940468, 2017). "In addition, in vivo and clinical studies are a focus of further investigations to validate the potential application of HHT and HT in treating interferonopathy and autoimmune diseases caused by dysregulation of the cGAS-STING pathway." (PMID 28771599, 2017). "Furthermore, aberrant activation of the cGAS-STING signaling pathway is closely associated with the occurrence of autoimmune diseases, which may be due to immune dysregulation resulted from excessive type I IFN production." (PMID 40165656, 2025). "Hence, We think that TTN could be a modulator for the management of inflammatory or autoimmune diseases that are caused by the cGAS-SITNG pathway." (PMID 39148120, 2024). "It was demonstrated that cGAS activation causes autoimmune diseases in Trex1-/- and DNaseII-/- mice, suggesting that inhibiting cGAS could prevent and treat some human autoimmune diseases triggered by self-DNA; and tonic prime-boost of STING signaling mediates Niemann–Pick disease type C." (PMID 38999073, 2024). "Moreover, the aberrant activation of cGAS is also linked to other autoimmune diseases and aging." (PMID 29760876, 2018). "While hyperactivation of cGAS leads to autoimmune diseases, its inactivation contributes to immune evasion and resistance to immunotherapies." (PMID 41999888, 2026). "Recent studies reveal that transposon-derived nucleic acids can activate innate immune sensors (e.g., TLRs, cGAS-STING), triggering chronic inflammation—a hallmark of aging, cancer, and autoimmune diseases." (PMID 41459148, 2025). "Recent research has linked cGAS-STING signaling to the development and progression of autoimmune diseases." (PMID 40165656, 2025). "While cGAS-STING signaling is crucial for antiviral defense and immune regulation, its dysregulation is implicated in autoimmune diseases such as systemic lupus erythematosus (SLE)." (PMID 40697819, 2025). "Since KDM4B specifically demethylates cGAS at K350, and Kdm4b knockout inactivates cGAS in autoimmune disease, we investigated the significance of cGAS K350 methylation in self-DNA-induced autoimmunity in vivo." (PMID 40595456, 2025). "The functional implications of cGAS in various disease contexts, including infectious diseases, autoinflammatory diseases, autoimmune diseases, aging, and cancers, are also covered." (PMID 40470467, 2025). "Mutations in genes encoding proteins involved in cGAS-STING or RIG-I/MDA5-MAVS pathways tend to be strongly linked to autoinflammatory and autoimmune diseases." (PMID 40362284, 2025). "In the context of autoimmune diseases, the ubiquitination of the cGAS-STING pathway can interact with IRF3/IRF7." (PMID 40028324, 2025). "Our data demonstrate that double-stranded DNA accumulates in the cytosol in autoimmune disease, leading to cGAS overactivation and elevated IFN production." (PMID 40595456, 2025). "It serves as a ligand for the cyclic GMP-AMP synthase/stimulator of interferon genes (cGAS/STING) pathway, which activates innate immune responses and has been linked to the pathogenesis of autoimmune diseases such as systemic lupus erythematosus (SLE)." (PMID 40442839, 2025). "Aspirin directly suppresses cGAS and thus exhibits promising potential in treating cGAS-driven autoimmune diseases, such as AGS." (PMID 38578631, 2024).
autoimmune disease (continued). "Loss-of-function mutations of the TREX1 gene are linked to autoimmune diseases such as Aicardi–Goutières syndrome, and mice deficient in TREX1 develop lethal inflammation in a cGAS-dependent manner." (PMID 39254994, 2024). "Targeted regulation of the cGAS-STING pathway to stabilize cytokines at normal levels is an important direction for autoimmune disease treatment and prevention." (PMID 39148120, 2024). "Research has demonstrated that TREX1 deficiency has a close association with various autoimmune diseases (e.g., AGS, SLE) and that in TREX1-deficient mouse models, deletion of cGAS or STING can ameliorate these disease phenotypes." (PMID 39737190, 2024). "It is suggested that TTN has a good therapeutic effect on cGAS-STING pathway-mediated autoimmune diseases." (PMID 39148120, 2024). "In summary, cGAS–STING promotes the susceptibility and severity of autoimmune diseases and amplifies the autoimmune reaction of SLE." (PMID 38525112, 2024). "These compounds introduced a novel class of hcGAS inhibitors that are active in cells, presenting a new chemical framework for creating probes to investigate cGAS function and develop treatments for autoimmune diseases." (PMID 38999073, 2024). "It is noteworthy that the hyperactivation of the cGAS–STING pathway and the resulting IFN-I responses are implicated in numerous inflammatory and autoimmune diseases." (PMID 39125448, 2024). "The role of cGAS on the innate immune regulation was first found in pathogen infection and autoimmune diseases." (PMID 38515746, 2024). "Inhibitors of the cGAS-STING pathway are also potential drugs against autoimmune diseases and cancers." (PMID 38999073, 2024). "Compounds like Acrinamin and Oxychloroquine show potential in blocking cGAS activation, offering new avenues for treating autoimmune disorders." (PMID 39737190, 2024). "In recent years, accumulating studies indicated that the abnormal activation of the natural immune cGAS-STING signaling pathway modulated by the nucleic acid receptor cGAS closely associated with the development and occurrence of autoimmune diseases (AID)." (PMID 37781360, 2023). "Two classes of cGAS inhibitors have been developed for the treatment of inflammatory and autoimmune diseases." (PMID 37932533, 2023). "Although the exact mechanism for PAH inhibition of cGAS remains elusive, PAHs have been demonstrated to effectively inhibit cGAS-STING signaling and can be developed as therapeutics for the treatment of cGAS-mediated autoimmune diseases." (PMID 37354378, 2023). "In inflammatory and autoimmune diseases, the cGAS-STING pathway promotes inflammatory molecule secretion and recruitment, induces cell apoptosis, and aggravates the occurrence of fibrosis." (PMID 37600809, 2023). "Recently, many researchers have revealed that the regulatory role of the cGAS pathway in autoimmune diseases, including Aicardi Goutières syndrome (AGS), systemic lupus erythematosus (SLE) and Rheumatoid arthritis (RA)." (PMID 37834184, 2023). "In recent years, small molecules targeting MITA/STING or cGAS have been developed for potential application in cancer immunotherapy or the treatment of inflammatory and autoimmune diseases." (PMID 37932533, 2023). "Cyclic guanosine monophosphate-adenosine monophosphate synthase (cGAS) has recently been identified as key cytosolic DNA signal that mediates type I IFN signaling in autoimmune diseases." (PMID 37268977, 2023). "Extensive studies have revealed the essential roles of cGAS in multiple biological processes, including pathogen invasion and autoimmune diseases." (PMID 37228597, 2023). "Recently, cGAS-STING signaling has been demonstrated to be associated with various diseases, including inflammation, autoimmune diseases, metabolic disorders, and tumors." (PMID 37020586, 2023). "Research has shown that the cyclic GMP-AMP synthase-stimulator of interferon genes (cGAS-STING) pathway is the cause of various inflammatory and autoimmune diseases." (PMID 37648705, 2023).
autoimmune disease (continued). "This suggests that Glab has the potential to be an effective drug candidate for autoimmune diseases mediated by the cGAS-STING signaling pathway." (PMID 38066431, 2023). "Defects arising from RNase H2 are linked to lethal autoimmune diseases including AGS and SLE, with massive IFNs in a cGAS-STING-dependent manner." (PMID 39872301, 2023). "In vivo studies on the functions of these selective cGAS inhibitors are needed to validate their roles in the intervention of inflammatory and autoimmune diseases in the future." (PMID 37932533, 2023). "Altogether, these results demonstrated that XQ2B efficiently attenuated systemic inflammation in Trex1-/- mice, highlighting the therapeutic potential of cGAS-specific inhibitors targeting protein-DNA interface in cGAS-related autoimmune diseases." (PMID 37783727, 2023). "Overall, the review highlights that inhibiting cGAS-STING-TBK1 signaling is an attractive strategy for autoimmune disease therapy." (PMID 36172373, 2022). "Currently, the blocking of cGAS-STING pathways but also TLR are intensively discussed as potential therapeutic targets for the treatment of autoimmune diseases, for example SLE." (PMID 35223833, 2022). "The cGAS-STING pathway has been confirmed not only to be involved in autoimmune diseases but also to mediate inflammatory responses." (PMID 35812407, 2022). "Undoubtedly, considering the central immune response function of the cGAS-STING pathway, although it is still a long way to go, the cGAS-STING axis already became a promising therapeutic target for cancer or autoimmune disease treatment." (PMID 36591232, 2022). "Activation of the cGAS-STING pathway is a double-edged sword that plays not only a crucial function in fighting viruses and bacteria but also an aberrant activation of cGAS by its DNA, which can provoke autoimmune disorders." (PMID 36189314, 2022). "cGAS cannot distinguish between pathogen-derived dsDNA and endogenic dsDNA; thus the cGAS pathway was activated with dsDNA accumulation in mutant cells, leading to autoimmune disease." (PMID 35280696, 2022). "When genomic instability leads to DNA damage or mitochondrial stress, the activation of cGAS can lead to autoimmune diseases and metabolic dysfunctions (Li and Chen, 2018; Bai and Liu, 2019)." (PMID 35536585, 2022). "While the cGAS-STING signaling pathway plays a critical role in resisting pathogen invasion, excessive activation of this pathway can cause chronic inflammation, autoimmune disease, and cancer." (PMID 35185917, 2022). "cGAS thereby plays a key role in a variety of diseases including infection, autoimmune diseases, and cancer by modulating the immune response." (PMID 35536585, 2022). "Herein, we focus on the key pathways mediated by cGAS-STING and various cGAS-STING-TBK1 signaling related autoimmune diseases, as well as the recent development of cGAS, STING, or TBK1 selective inhibitors." (PMID 36172373, 2022). "For instance, inhibitors targeting cGAS significantly downregulated IFN expression in TREX1-/- PMBCs in AGS model mice, showing excellent potential for drug development in the treatment of autoimmune diseases caused by DNA accumulation such as AGS and SLE." (PMID 36172373, 2022). "Nerveless, cGAS inhibitors still can be a good complement to therapeutic regimens for the treatment of DNA-dependent autoimmune diseases." (PMID 36172373, 2022). "Suramin is being touted in a clinical trial for inhibiting the cGAS activation in human autoimmune disease." (PMID 36139387, 2022). "Several studies on 2′3′-cGAMP in metazoans exist, and the cGAS-STING pathway has been critically implicated in inflammatory injury, aging, autoimmune diseases, and cancer immunotherapy." (PMID 36619988, 2022). "The cGAS-STING signaling plays an integral role in the host immune response, and the abnormal activation of cGAS-STING is highly related to various autoimmune diseases." (PMID 36172373, 2022).
autoimmune disease (continued). "cGAS-STING signaling is emerging as a significant regulator of pathogenic infection, development of cancer or autoimmune diseases, or inflammatory disorders." (PMID 36139387, 2022). "Although cGAS indispensable for pathogen defense, its aberrant activation by endogenous DNA is a key driver of autoimmune diseases." (PMID 33767433, 2021). "Given the critical role of cGAS in microbial infection defense and autoimmune diseases, it is urgent to understand the regulation of cGAS activation and expression." (PMID 33767433, 2021). "Modulating the cGAS-STING pathway and expression of IFN-I and related inflammatory factors are important in alleviating autoimmune diseases caused by immune abnormalities." (PMID 34867409, 2021). "Hyperactivation of cGAS signaling contributes to autoimmune diseases but serves as an adjuvant for anticancer immune therapy." (PMID 33927185, 2021). "Previous studies demonstrated that cGAS pathway is related to the inflammation amplification in a variety of autoimmune diseases." (PMID 34718330, 2021). "Cyclic GMP-AMP synthase (cGAS), a key sensor of intracellular DNA, is essential for eliciting innate immunity against infection, whereas aberrant activation of cGAS by endogenous DNA promotes severe autoimmune diseases." (PMID 33767433, 2021). "Collectively, our study not only reveals a novel regulatory mechanism of cGAS expression by miRNAs but also identifies a potential therapy for cGAS-related autoimmune diseases." (PMID 33767433, 2021). "Our review would be significant for understanding the precise modulation of cGAS activity, providing the foundation for the future development of drugs against cGAS-triggering autoimmune diseases such as Aicardi-Gourtières syndrome." (PMID 34899698, 2021). "Aberrant activation of cGAS stimulated by self-DNA has been enrolled in multiple autoimmune diseases, especially SLE." (PMID 34718330, 2021). "On the other hand, abnormal activation of the cGAS-STING pathway is the main cause of inflammation and autoimmune diseases." (PMID 34867409, 2021). "Abnormal activation of cGAS by self-DNA is linked to severe autoimmune diseases such as AGS, and inhibition of cGAS provides a powerful therapeutic strategy." (PMID 33968056, 2021). "Activation of the cGAS-STING signal pathway triggered by nucleic acids is involved in the pathogenesis of various autoimmune diseases, including Aicardi–Goutieres Syndrome (AGS), systemic lupus erythematosus (SLE), familial chilblain lupus." (PMID 34956229, 2021). "It elucidates their functions in antiviral response, autoimmune diseases and cancer, thus obtaining a better understanding of the regulatory role of alternative splicing in the cGAS-STING signaling pathway and innate immunity." (PMID 34868032, 2021). "Recent studies have identified cyclic GMP-AMP synthase (cGAS) as an important target for treating autoimmune diseases, and several inhibitors of human cGAS (hcGAS) and their structures in complexation with hcGAS have been reported." (PMID 33503880, 2021). "Given the essential function of cGAS in cytosolic DNA sensing and various pathological conditions including both autoimmune diseases and cancer, research efforts have also been devoted to developing small molecules that modulate cGAS activity." (PMID 33927185, 2021). "While detection of foreign DNA plays an indispensable role in pathogen defense, aberrant activation of cGAS by self-DNA can promote severe autoimmune diseases." (PMID 33968056, 2021). "We set out to investigate the role of the cGAS-STING signal transduction pathway in autoreactive GCB cells using a murine mixed BM chimera model that mimics the archetypal autoimmune disease SLE." (PMID 34938294, 2021). "This will lead to abnormal activity of the cGAS/STING pathway, causing autoinflammation and autoimmune disease and even inflammation-associated cancers." (PMID 35006429, 2020).